RNU6-907P (RNA, U6 small nuclear 907, pseudogene)
Gene: Small nuclear RNA gene on chromosome 4 (89,130,852 to 89,130,953, forward strand). Ensembl gene ENSG00000212226.
Homologues: Orthologues: macaque U6 (87% identical), chimpanzee U6 (86% identical), mouse Gm56305 (53% identical). Paralogues in human: RNU6-1131P (76% identical), RNU6-209P (76% identical), RNU6-333P (75% identical), RNU6-411P (75% identical), RNU6-510P (75% identical), RNU6-537P (75% identical), RNU6-820P (75% identical), RNU6-1287P (75% identical), RNU6-1304P (75% identical), RNU6-224P (75% identical), RNU6-315P (75% identical), RNU6-38P (75% identical), and 1285 more.